RARG (retinoic acid receptor gamma)
Diseases named in the same sentence as RARG in open-access papers (continued):
Sharing a sentence is not in itself a finding about the gene and the disease.
schizophrenia (1 paper, 2016). A major psychotic disorder characterized by abnormalities in the perception or expression of reality. "This study presents evidence for down-regulation of the nuclear receptors NR4A1, NR4A2, RXRB, and KLF4 mRNAs in the DLPFC in schizophrenia and evidence of reduced RARG and RXRG expression in females with schizophrenia." (PMID 27992436, 2016). "We detected decreased expression of RARG and NR4A2 mRNAs in females with schizophrenia (p<0.05)." (PMID 27992436, 2016). "Our finding of decreased RARG and RXRG mRNA levels in females with schizophrenia may be related to changes found in estrogen and/or estrogen receptors (ER) signaling." (PMID 27992436, 2016).
Sepsis (1 paper, 2017). Sepsis is defined as life-threatening organ dysfunction caused by a dysregulated host response to infection. "Next we used a mouse model of systemic inflammation that resembles clinical sepsis to examine the role of RARγ in cell death in vivo." (PMID 28871172, 2017).
synovial sarcoma (1 paper, 2006). "Additionally, many other genes that have been previously related to synovial sarcomas, such as the SSX4 gene, EGFR and SALL2, components of the retinoic acid pathway (CRABP1 and RARG) as well as retinoic acid induced genes (IRX5 and TGFβ2), were also included in this module." (PMID 16503973, 2006).
teratocarcinoma (1 paper, 2010). A germ cell tumor characterized by the presence of an embryonal carcinoma component and a teratoma component. "Although, it is unknown how RA signals stimulate GATA4/6 expression in this system, previous studies of pluripotent F9 teratocarcinoma cells have identified GATA4 and GATA6 as transcriptional targets of RARγ and RARβ2 signaling complexes, respectively." (PMID 20644631, 2010).
Thromboembolism (1 paper, 2025). The formation of a blood clot inside a blood vessel that subsequently travels through the blood stream from the site where it formed to another location in the body, generally leading to vascular occlusion at the distant site. "Future studies should prioritize multicenter cohorts to validate PDA and thromboembolism as risk factors, mechanistic investigations of genetic or inflammatory pathways (e.g., RARG or VEGF signaling), and longitudinal designs to assess late-onset toxicity." (PMID 40322385, 2025).
tumor (55 papers, 2004 to 2025). "Sequencing of the fusion transcript showed also that NUP98 exon 12 was fused in frame to RARG exon 4, in the first patient described, and the Wilms' tumor (WT1) mutation was also identified." (PMID 31709264, 2019). "Patients with higher RARγ expression are significantly associated with larger tumor size, distant metastasis and high TNM stage of HCC." (PMID 27756432, 2016). "In vitro experiments indicated that the rise in RARγ was functionally linked to promotion of tumor growth and inhibition of differentiation." (PMID 22920668, 2012). "Although this study primarily utilized THP-1-derived macrophages, the observed upregulation in RARγ and RXRγ during M2 polarization suggests that this regulatory mechanism may be conserved in primary human macrophages and tumor-associated macrophages in vivo." (PMID 40807274, 2025). "These NRs were not differentially expressed in ERα/PGR/HER2 subgroups, with the exception of RARγ whose expression appeared to be lower in HER2-positive than in HER2-negative tumours, although statistical significance for association with HER2 status was not reached (p = 0.076)." (PMID 26280373, 2015). "Other workers have reported that upregulated expression of RARγ in human tissues correlates with tumour size and distant metastases and negatively with patient survival." (PMID 40362593, 2025). "The presence of multiple RARγ isoforms in each tumor indicates that the biological functions of RARγ should be interpreted as a collective effect of these isoforms, rather than a single RARγ molecule." (PMID 39744424, 2025). "RAR exists in three isoforms—RARα, RARβ, and RARγ—each with distinct tissue distributions and roles: RARα is expressed in various tissues, RARβ plays a key role in neurogenesis and tumor suppression, and RARγ is vital for skin and bone development." (PMID 40926269, 2025). "Although this was observed in a tumor model, the ability of lactylation to affect RARγ expression provides a new possibility for future research on the impact of lactylation on bone metabolism." (PMID 40511385, 2025). "This study demonstrates the critical role of the nuclear receptor RARγ in regulating M2 macrophage polarization and its impact on tumor growth in the TME." (PMID 40807274, 2025). "Knockdown of RARγ similarly prevented in vitro and in vivo tumor growth in various types of human cancer cells other than HNC." (PMID 39744424, 2025). "Using 20 pairs of fresh frozen OSCCs and their corresponding adjacent non-tumor epithelia, we confirmed that RARγ1, 2, 4 were the main RARγ isoforms expressed in tumor tissues." (PMID 39744424, 2025). "Immunohistochemical study was also performed to study the expression patterns of RARγ isoforms in formalin-fixed, paraffin-embedded tissues from normal oropharyngeal epithelia (n=10), non-tumor epithelia adjacent to OSCC (n=10) and OSCCs (n=10)." (PMID 39744424, 2025). "Recent research has demonstrated that lactate drives macrophage remodeling by inhibiting RARγ expression, enhancing interleukin-6 levels in the tumor microenvironment, and activating the STAT3 signaling pathway to promote CRC progression." (PMID 40900785, 2025). "In conclusion, this study demonstrates that RARγ plays a crucial role in the polarization of M2 macrophages and tumor growth." (PMID 40807274, 2025). "Future studies should aim to incorporate primary keratinocyte models or normal oral epithelial cells to distinguish between tumor-specific alterations and baseline RARγ functions." (PMID 41274504, 2025). "In summary, the involvement of RARγ in malignancies and its potential as a therapeutic target have been confirmed across various contexts, emphasising its significance for anti‐tumour interventions." (PMID 39724264, 2025).
tumor (continued). "Lactate induces histone lactylation in macrophages, repressing anti‐tumor genes (e.g., RARγ) while activating the transcription of immunosuppressive IL‐6." (PMID 40904700, 2025). "Epigenetic modifications suppress anti‐tumor genes such as RARγ while activating immunosuppressive IL‐6/STAT3 signaling." (PMID 40904700, 2025). "The anti-tumor effect of acacetin in vivo was studied in BALB/c mice subcutaneously transplanted with HepG2/RARγ liver cancer cells." (PMID 39459239, 2024). "In CRC cells, tumor-derived lactate fuels H3K18 lactylation to prohibit RARγ gene transcription in macrophages, consequently enhancing IL-6 levels in the TME and endowing macrophages with tumor-promoting functions." (PMID 38812044, 2024). "This study highlights the role of histone lactylation-driven RARγ downregulation in promoting pro-inflammatory and pro-tumor phenotypes in macrophages, revealing a novel mechanism by which histone lactylation in TAMs advances tumor progression." (PMID 39662177, 2024). "Further, the knockdown of RARγ in A2780 xenografts resulted in decreased tumor weight and volume along with reduced expression of RARγ, Ki-67, and PCNA." (PMID 39077471, 2024). "The mechanism of the tumor-suppressive effects by blocking RARγ signaling was examined by a cell cycle analysis, apoptosis assays, RNA sequencing and Western blotting." (PMID 37198667, 2023). "Investigators have reported that RARγ overexpression was increased during tumor progression and correlated with a significantly worse prognosis." (PMID 37569466, 2023). "miR30a-5p is low in patients’ cancer cells, a tumor suppressor, and downregulates expression of RARγ." (PMID 37569466, 2023). "From these findings, RARγ was proposed as a possible tumour suppressor because a significant decrease in expression was seen for squamous cell carcinoma biopsies." (PMID 36768694, 2023). "Given that RARγ inhibition alone cannot induce cancer cell death but can inhibit DNA repair and that Gem and RARγ inhibition have different tumor-suppressive mechanisms, combining RARγ inhibition with DNA-damaging agents is rational." (PMID 37198667, 2023). "We compared the mRNA level of RARG between ovrian normal and tumor tissues with the Wilcoxon rank sum test.The R package “limma” was used to analyze the differences in RARG expression between different clinical subgroups." (PMID 36523991, 2022). "One such study determined the expression of RARs in normal and malignant tissues from 76 patients with NSCLC and showed that tumor cells have overexpressed RXRα and RARα and reduced RXRβ, RARβ, and RARγ." (PMID 35631448, 2022). "Immunohistochemistry and qRT−PCR experiments were conducted to determine the differential expression of RARG between ovarian normal and tumor tissues." (PMID 36523991, 2022). "On the flip side, RARG can also be a tumor suppressor that inhibits the proliferation and invasion of cancer cells." (PMID 36523991, 2022). "In cellular experiments in vivo, knockdown of RARG significantly reduced tumor growth in nude mice, decreased expression levels of Ki-67 and proliferation cell nuclear antigen (PCNA)." (PMID 36523991, 2022). "While both PCa cells and normal prostate epithelium express RARα and RARγ together, in the case of PCa, the tumor cells appear to be dependent on active RARγ for their proliferation and survival." (PMID 33807298, 2021). "73% of CRCs overexpress RARG mRNA and protein compared with 20% for adjacent non-tumor colorectal tissue (20%)." (PMID 33807298, 2021). "The findings showed that RARα, RARβ, RARγ, and RXRγ were present in significantly lower levels in the tumor tissues." (PMID 32012980, 2020). "In contrast, RARγ has also been reported as a tumor suppression factor that inhibits cancer cells proliferation and invasion." (PMID 27756432, 2016).
tumor (continued). "This showed that the top 8 NR, namely ERα, PGR, DAX1, TLX, PNR, RARγ, RARα and Rev-erbAβ provide the lowest error rate, highlighting these NRs as the most important variables for differentiating the two tumour clusters." (PMID 26280373, 2015). "Knockdown of RARγ in MMTV-Myc-derived cancer cells impaired tumor growth in a xenograft model and induced markers of cell-cycle arrest, differentiation and acinar-like morphogenesis in three-dimensional cultures." (PMID 22920668, 2012). "Given the pro-tumorigenic activity of RARγ, we examined the effect of RARγ knockdown on tumor invasiveness by generating three-dimensional cultures." (PMID 22920668, 2012). "Overall, our results bring new insights to our understanding of the effect of the c-Myc oncogene on RAR isotype expression, c-Myc/RAR isotype reciprocal relationships, and the novel tumor-promoting role of RARγ." (PMID 22920668, 2012). "In contrast, treatment of MMTV-Neu transgenic mice with the RAR isotype pan-agonist ATRA, which also activates RARγ, promoted tumor growth." (PMID 22920668, 2012). "In another study, tumor-derived lactate drove macrophages to downregulate RARγ gene transcription through histone lactylation, thereby promoting tumor growth, and RARγ also plays an important role in promoting osteoblast differentiation." (PMID 40511385, 2025). "Our findings indicate the potential therapeutic significance of targeting M2 macrophages, which are known to promote tumor progression, suggesting that RARγ could serve as a promising target for cancer treatment." (PMID 40807274, 2025). "In future studies, we plan to use more realistic in vivo experimental models to validate the drug's efficacy and provide more detailed molecular biological evidence to elucidate the complete and specific molecular mechanisms through which ZSH‐2208 exerts its anti‐tumour effects by regulating RARγ." (PMID 39724264, 2025). "Similarly, in colon cancer, tumor-derived lactate up-regulates H3K18la in TIMs, inhibiting RARγ transcription and fostering tumor development." (PMID 40948941, 2025). "In summary, the data to date indicate a tumor suppressive function for RARγ in OCSCC." (PMID 41274504, 2025). "RARG by signaling pathway may contribute to tumor progression by modulating cellular differentiation, proliferation, and apoptosis." (PMID 40969325, 2025). "It remains unclear whether these inconsistent observations result from the differential expression of RARγ isoform(s) across tumor types or from tumor-specific effects of RARγ." (PMID 39744424, 2025). "Although these compounds are still under development as final drugs, the anti-tumor effects observed from AGN205728 further strengthen the idea that oncogenic RARγ-targeting could be an effective treatment for various types of human cancers." (PMID 39744424, 2025). "We hypothesize that an RARγ agonist like IRX4647 could exert substantial anti-neoplastic actions as a single agent or when combined with checkpoint blockade to augment anti-tumor responses in diverse human cancers." (PMID 37689790, 2023). "RARα, RARβ, and RARγ mRNAs were expressed by normal and tumor samples." (PMID 37569466, 2023). "Furthermore, using patient-derived PDAC organoids, we confirmed the tumor-suppressive effect of RARγ inhibition and indicated the synergistic effects of RARγ inhibition with gemcitabine." (PMID 37198667, 2023). "However, RARγ inhibition exerted synergistic tumor-suppressive effects with Gem by downregulating DNA repair genes." (PMID 37198667, 2023). "Tumour cell growth by A2780 cells in nude mice was reduced by the knockdown of RARγ." (PMID 36768694, 2023). "To explore the correlation between RARG and clinicopathological parameters, we excluded patients with unknown tumor stage, tumor grade and treatment outcomes." (PMID 36523991, 2022). "The weight of transplanted tumor also decreased significantly after RARG knockout." (PMID 36523991, 2022). "RARG has also been suggested to be a tumor suppressor in keratinocytes." (PMID 30120411, 2019).
tumor (continued). "The goal was to determine whether RARγ expression was enhanced and whether this increase affected c-Myc-induced tumor growth." (PMID 22920668, 2012). "Finally, the expression changes of RARG and miR-96 cluster members were validated in an independent cohort of 36 matching tumor/normal prostate tissue pairs obtained from Roswell Park, corroborating observations in TCGA-PRAD and MSKCC cohorts that furthermore associated with Gleason sum." (PMID 30120411, 2019). "Knockdown of RARγ induced remarkable growth inhibition in esophageal (CE146T), breast (MCF7), and colon (SW620) cancer cells, and abolished tumor formation in nude mice xenografted with lung (A549) and colon (SW620) cancer cells." (PMID 39744424, 2025). "Knockdown of RARγ abolished proliferation of cultured HNC cells, and completely prevented tumor growth in xenografted nude mice." (PMID 39744424, 2025). "The inhibition of RARγ disrupted M2 polarization and diminished the tumor-supportive functions of macrophages in the TME, thereby reducing tumor growth in a 3D spheroid model." (PMID 40807274, 2025). "Knockdown of RARγ similarly abolished tumor formation in nude mice xenografted with SAS cells, implying the clinical potential of RARγ-targeting approach in HNC." (PMID 39744424, 2025). "Knockdown of RARγ abolished proliferation of HNC cells in vitro, and effectively prevented tumor growth in vivo." (PMID 39744424, 2025). "Specifically, tumor-derived lactate inhibits RARγ gene transcription in macrophages through H3K18la, activating TRAF6-IL-6-STAT3 signaling to support tumor growth." (PMID 39662177, 2024). "This study clarified the function of RARγ signaling in PDAC progression and demonstrated the tumor-suppressive effect of selective blockade of RARγ signaling against PDAC." (PMID 37198667, 2023). "As follows, miR-30a is a tumor suppressor for many cancers and integrates ATRA biosynthesis and RARγ expression." (PMID 37569466, 2023). "RARγ is activated by nM levels of ATRA and an oncogene by virtue of overexpression which promotes tumor growth." (PMID 37569466, 2023). "Our results suggest that RARγ is involved in the repression of RARβ and CRBP1 expression, both of which have a tumor-suppressive function." (PMID 22920668, 2012). "Notably, mice treated with the RARγ agonist IRX4647 and an anti-PD-L1 agent statistically-significantly elevated CD4+ T helper cells in the spleen and tumor." (PMID 37689790, 2023). "The relative increase in RARγ isotype expression relative to the α and β isotypes correlates with tumor progression and lack of expression of RARα target genes involved in cell-cycle arrest and differentiation." (PMID 22920668, 2012). "Modulation of the RARα/β to RARγ expression in mammary glands of normal mice, oncomice, and human mammary cell lines through the alteration of RAR-target gene expression affected cell proliferation, survival and tumor growth." (PMID 22920668, 2012). "The growth of tumour cells was also inhibited more than that of normal cells when RARβ together with RARγ, but not RARα alone, were antagonised." (PMID 15266311, 2004). "For instance, while RARγ is considered an oncogene in some human cancers 15, contradictory reports also demonstrated that RARγ could be a tumor suppressor gene rather than an oncogene 16,17." (PMID 39744424, 2025). "Notably, RARγ peaks were highly enriched near genes involved in cell surface signaling and adhesion, including SERPINE1, ITGB3, ITGA6, and COL4A2, which are known to control both epithelial plasticity and tumor progression." (PMID 41274504, 2025).
tumor (continued). "Our results showed that in the small intestine, RARG (Retinoic Acid Receptor Gamma) show the highest expression, while fibroblasts from tumors predominantly express LPAR1 (Lysophosphatidic Acid Receptor 1), highlighting a possible importance in tumor tissue formation." (PMID 39766077, 2024). "Therefore, RARβ could act as tumor suppressor even in the absence of ATRA, and RARβ loss expression gives AP-1 over-expression, which could abrogate the growth-inhibitory effects of ATRA through RARα and RARγ, resulting in retinoid resistance." (PMID 32012980, 2020).